GCAT (glycine C-acetyltransferase)
Description:
Pyridoxal phosphate (PLP) dependent enzyme, which catalyzes the cleavage of 2-amino-3-oxobutanoate to glycine and acetyl-CoA.
Synonyms: KBL
Tractability: PROTAC: ubiquitination databases record sites on it; its protein half-life has been measured.
Gene: Protein-coding gene on chromosome 22 (37,807,872 to 37,817,386, forward strand). Ensembl gene ENSG00000100116.
Subcellular location: Mitochondrion; Nucleus
Subcellular location (Human Protein Atlas): Nuclear speckles; Mitochondria; Nucleoplasm
Gene Ontology:
Molecular function: glycine C-acetyltransferase activity; pyridoxal phosphate binding; transferase activity
Biological process: amino acid metabolic process; L-threonine catabolic process
Cellular component: mitochondrion; nuclear speck; nucleoplasm; nucleus
Genetic constraint (gnomAD): Loss-of-function variants: 27 observed, 35.66 expected, observed/expected ratio (o/e) 0.76, 90% interval 0.56 to 1.04. The upper end of that interval is the gene's LOEUF score, 1.04, which puts it in group 4 of 6, group 1 being the genes least tolerant of losing a copy. Missense variants: 547 observed, 555.1 expected, observed/expected ratio (o/e) 0.99, 90% interval 0.92 to 1.06. Synonymous variants: 218 observed, 226.51 expected, observed/expected ratio (o/e) 0.96, 90% interval 0.86 to 1.08.
Homologues: Orthologues: chimpanzee GCAT (99% identical), macaque GCAT (97% identical), guinea pig GCAT (92% identical), dog GCAT (91% identical), mouse Gcat (91% identical), pig GCAT (88% identical), rat Gcat (81% identical), tropical clawed frog gcat (78% identical), zebrafish gcat (72% identical), rabbit GCAT (69% identical), Drosophila melanogaster Gcat (65% identical), Caenorhabditis elegans T25B9.1 (59% identical). Paralogues in human: ALAS2 (33% identical), ALAS1 (32% identical), SPTLC2 (31% identical), SPTLC3 (28% identical), SPTLC1 (24% identical).
Diseases named in the same sentence as GCAT in open-access papers:
GCAT is named in the same sentence as 15 diseases in open-access papers, as found by Europe PMC text mining. Sharing a sentence is not in itself a finding about the gene and the disease. The quoted sentences say what the papers report.
alopecia (1 paper, 2018). Hair loss usually from the scalp. "However, no growth retardation or obvious macroscopic abnormalities including premature aging phenotypes, such as hair greying, alopecia, or kyphosis, were observed in Gcat m/m mice for at least 9 months after birth, even though they did not have the GCAT protein." (PMID 29323231, 2018).
Alzheimer disease (1 paper, 2025). A progressive, neurodegenerative disease characterized by loss of function and death of nerve cells in several areas of the brain leading to loss of cognitive function such as memory and language. "Moreover, GCAT protein levels are markedly reduced in the brains of patients with late-onset Alzheimer’s disease, leading to the accumulation of its downstream metabolite methylglyoxal and its glycation end-products." (PMID 41351017, 2025).
colon adenocarcinoma (1 paper, 2023). "GCAT is ubiquitously expressed in the pancreas and prostate and is overexpressed in uterine corpus endometrial carcinoma, PRAD, lung adenocarcinoma/squamous carcinoma, invasive breast carcinoma, and colon adenocarcinoma." (PMID 37007952, 2023).
Stroke (1 paper, 2023). Sudden impairment of blood flow to a part of the brain due to occlusion or rupture of an artery to the brain. "Based on the role of metabolism in stroke, we extracted seven genes related to the “porphyrin metabolism” and “glycine, serine and threonine metabolism” pathways, including ALAS2, FECH, COX10, GCAT, HMBS, PGAM2, and AOC2." (PMID 36968495, 2023).
tumor (2 papers, 2023 to 2024). "Intriguingly, we found that the mRNA levels of low-risk genes NUCB1 and GCAT were elevated in tumor tissues more than those in normal tissues, but they were lower in stage IV than in stages I–III." (PMID 37007952, 2023). "In our risk signature, we found that the low-risk genes NUCB1 and GCAT were higher in tumor tissues than in adjacent normal tissues in PRAD; however, their expression levels in the high stage were lower than those in the low stage and that the risk signature performed well in prognosis prediction." (PMID 37007952, 2023).
heart disease (1 paper, 2021). "Further potentially disease-relevant protein candidates without a known functional relation to hypertrophy, fibrosis or decompensated heart disease were SLTM, HNRNPLL, FIP1L1, RNMT, KRT18 and PUF60 and the downregulated NUDT4, GCAT, KIDINS220 and ARVCF." (PMID 34937869, 2021).
infection (1 paper, 2015). The state of being infected such as from the introduction of a foreign agent such as serum, vaccine, antigenic substance or organism. "Moreover, overexpression of GCAT in TIG102 by infection with lentivirus including the cDNA of GCAT restored the respiration defects." (PMID 26000717, 2015).
GCAT also shares sentences with these, for which no sentence is quoted: angiomyolipoma (1 paper); cancer (1); glioma (1); invasive breast carcinoma (1); kidney (1); lung adenocarcinoma (1); squamous carcinoma (1); uterine corpus endometrial carcinoma (1).